ANXA3 (annexin A3)
Diseases named in the same sentence as ANXA3 in open-access papers (continued):
Sharing a sentence is not in itself a finding about the gene and the disease.
Stroke (3 papers, 2021 to 2023). Sudden impairment of blood flow to a part of the brain due to occlusion or rupture of an artery to the brain. "ANXA3 plays a role in regulation of cell growth, regulation of endothelial cell migration, maintenance of cellular phospholipids and signal transduction pathways and has been associated with stroke in animal studies." (PMID 37035297, 2023). "Co-expressed hub genes of EIF4E3, ZNF595, ZNF700, MATR3, ACKR4, ANXA3, SEPSECS-AS1, and RNF166 were significantly associated with AF-related stroke." (PMID 36952494, 2023). "In vivo administration of hADMSCs loaded with the therapeutic peptide p5 to post-stroke rats led to improvement in functional recovery and increased number of surviving transplanted cells, most likely by reducing the number of inflammatory ANXA3/IbaI-positive cells in the peri-infarcted region." (PMID 32378028, 2021). "Based on the results of DEG3 and ROC curves in GSE66724 and GSE58294, we filtered eight hub genes of AF-related stroke (AUC > 0.8), including EIF4E3, ZNF595, ZNF700, MATR3, ACKR4, ANXA3, SEPSECS-AS1, and RNF166." (PMID 36952494, 2023). "Hub genes EIF4E3, ZNF595, ZNF700, MATR3, ACKR4, ANXA3, SEPSECS-AS1, and RNF166 have potential as novel biomarkers and therapeutic targets in AF-related stroke." (PMID 36952494, 2023). "Results showed that the expression of EIF4E3, ANXA3, and hsa_circ_0018657 was significantly higher in AF-related stroke patients than those in AF patients without stroke, which was consistent with the bioinformatic analysis." (PMID 36952494, 2023). "The hub genes of EIF4E3, ZNF595, ZNF700, MATR3, ACKR4, ANXA3, SEPSECS-AS1, and RNF166 may link AF and secondary stroke." (PMID 36952494, 2023).
triple-negative breast carcinoma (3 papers, 2017 to 2025). An invasive breast carcinoma which is negative for expression of estrogen receptor (ER), progesterone receptor (PR), and human epidermal growth factor receptor 2 (HER2). "At histological level, less blood vessels were observed in H&E-stained tissue slides of triple negative breast cancer xenografts from mice pretreated with ANXA3-silencing shRNA plasmids." (PMID 34355022, 2021). "The highest expression of ANXA3 was detected in triple-negative breast cancer with poor prognosis as confirmed by the subsequent follow-up studies." (PMID 28497041, 2017). "Significantly (P < 0.002) higher level of ANXA3 was detected in triple-negative breast cancer compared to other subtypes." (PMID 28497041, 2017). "Currently, a first-class ANXA3 inhibitor has been tested in triple-negative breast cancer, the small molecule SL18, reported as ANXA3-specific, showed low toxicity and efficiency in vivo by inactivating the Wnt/β-catenin pathway." (PMID 40562609, 2025).
Anxiety (2 papers, 2020 to 2025). Intense feelings of nervousness, tension, or panic often arise in response to interpersonal stresses. "In this case, overactivation or suppression of these channels may regulate anxiety-related behaviors, suggesting that calcium homeostasis and membrane signaling proteins, such as ANXA3, may have evolved through similar neurobiological mechanisms." (PMID 41010398, 2025).
breast tumor (2 papers, 2018 to 2021). "In this study, we found that ANXA3 is significantly upregulated in breast tumor tissues from clinical biopsies." (PMID 29374148, 2018). "The results showed that ANXA3 knockdown promoted breast tumor growth." (PMID 29374148, 2018).
chronic periodontitis (2 papers, 2011 to 2020). A chronic inflammatory process that affects the tissues that surround and support the teeth. "In accordance with a previous report, myeloperoxidase, myosin 9, annexin A3, profilin-1, L-plastin (plastin-2/LCP1), S100A8, and S100A9 were detected at higher levels in chronic periodontitis patients compared to healthy individuals." (PMID 21794177, 2011).
colon adenocarcinoma (2 papers, 2018 to 2025). "We first examined the differential expression levels of maspin, ANXA3, LAP3, and PSMA1 in normal colonic mucosa vs. colon adenocarcinoma by 1D Western blotting." (PMID 29423100, 2018).
depression (2 papers, 2023 to 2025). "Our study showed that serum ANXA3 levels were significantly decreased in patients with major depressive disorder and were strongly associated with systemic inflammatory markers and severity of depression." (PMID 41010398, 2025). "Pairwise ROC analysis was performed to evaluate the ability of NLR and serum ANXA3 levels to discriminate between different Beck Depression Inventory (BDI) severity categories." (PMID 41010398, 2025). "Overall, these results indicate that higher depression severity is associated with elevated WBC, neutrophil, and platelet counts, NLR, and glucose levels, and reduced lymphocyte and ANXA3 levels." (PMID 41010398, 2025). "Future studies should include these parameters to better determine the independent contribution of ANXA3 to major depressive disorder." (PMID 41010398, 2025). "Machine learning-based visualization further demonstrated that mean serum ANXA3 levels decreased progressively across depression severity categories, with the highest levels in the minimal and mild groups and the lowest levels in the severe group." (PMID 41010398, 2025). "More comprehensive studies are needed to confirm our findings and investigate the role of ANXA3 in the pathophysiology of depression." (PMID 41010398, 2025). "In our study, we demonstrated that serum ANXA3 levels were significantly lower in patients with major depressive disorder than in healthy controls and that ANXA3 levels were negatively correlated with the neutrophil-to-lymphocyte ratio (NLR)." (PMID 41010398, 2025). "In our study, the significantly lower serum ANXA3 levels in patients with depression suggest that the calcium-binding annexin family may play a role in the pathophysiology of depression." (PMID 41010398, 2025). "Our findings suggest that ANXA3 may play an important role in the pathophysiology of depression and may serve as a potential biomarker, particularly for inflammation-related disorders in women." (PMID 41010398, 2025). "There was not statistically significant association between major depression status and Anxa3 levels." (PMID 41010398, 2025). "Similarly, lower glucose (OR = 0.91, p = 0.005) and reduced ANXA3 concentrations (OR = 0.50, p < 0.001) independently predicted greater depression severity." (PMID 41010398, 2025). "Further studies are needed to clarify its clinical utility and confirm whether ANXA3 alterations represent state or trait markers of depression." (PMID 41010398, 2025). "The robustness of our statistical model suggests that ANXA3 may have potential clinical significance in classifying depression severity." (PMID 41010398, 2025). "Assessing ANXA3 expression at the mRNA level in future studies will be important to determine whether the observed protein-level decreases are also reflected at the transcriptional level, thus strengthening the biological plausibility of ANXA3 as a biomarker of depression severity." (PMID 41010398, 2025). "ANXA3 may serve as a potential biomarker for identifying and monitoring the severity of depression." (PMID 41010398, 2025). "Because its association with major depressive disorder (MDD) is unclear, we aimed to compare serum ANXA3 levels in patients with MDD and healthy controls and to investigate their relationship with depression severity." (PMID 41010398, 2025). "We found that low ANXA3 levels, high NLR, and glucose dysregulation predicted greater depression severity." (PMID 41010398, 2025). "To facilitate interpretation, we have also reformatted the ordinal regression outputs into a concise summary table, which highlights the strong predictive role of ANXA3 and NLR in relation to depression severity." (PMID 41010398, 2025). "When discriminating between mild and moderate depression, NLR (cutoff > 2.22) had an AUC of 0.744 (95% CI: 0.593–0.863), while serum ANXA3 (cutoff ≤ 11.3) had an AUC of 0.917 (95% CI: 0.795–0.978) with perfect (100%) specificity." (PMID 41010398, 2025).
depression (continued). "Despite increasing evidence regarding the importance of annexin types in psychiatric disorders, serum ANXA3 levels have not been investigated in patients with major depressive disorder (MDD) and their relationship to depression severity has not been examined." (PMID 41010398, 2025).
Down syndrome (2 papers, 2019 to 2023). "The rest have a different cytogenetic location (TNFSF13B on chromosome 13, whilst ANXA3 and ANXA5 on chromosome 4), which seems to corroborate that Down Syndrome causes impairments to the complete genome." (PMID 31772502, 2019).
fibrosarcoma (2 papers, 2018 to 2024). A malignant mesenchymal fibroblastic neoplasm affecting the soft tissue and bone. "Three proteins: ANXA5, ANXA3, and MNS1 were identified to be significantly (p ≤ 0.05) differentially expressed in doxorubicin-resistant fibrosarcomas in comparison to doxorubicin-sensitive ones." (PMID 29443940, 2018).
Huntington disease (2 papers, 2015 to 2020). Huntington disease (HD) is a rare neurodegenerative disorder of the central nervous system characterized by unwanted choreatic movements, behavioral and psychiatric disturbances and dementia. "The five genes (PROK2, ZNF238, AQP9, CYSTM1 and ANXA3) that were validated independently in both cohorts present a candidate biomarker panel for stage determination and therapeutic readout in Huntington's disease." (PMID 25626709, 2015).
Kawasaki disease (2 papers, 2017 to 2023). A rare inflammatory disease characterized by an acute febrile, systemic, self-limiting, medium-vessel vasculitis primarily affecting children. "For Kawasaki disease, the expression level of ANXA3 could separate patients from healthy controls with F1 value of 0.97." (PMID 28771541, 2017).
papillary thyroid carcinoma (2 papers, 2012 to 2021). "In surgical tumor specimens from 25 thyroid papillary cancer patients receiving thyroidectomy, downregulation of ANXA3 was detected in tumor tissues compared to the adjacent non-tumor tissues." (PMID 34355022, 2021). "Jung EJ’s proteomic analyses revealed that annexin A3 was significantly decreased in papillary thyroid carcinoma at both the protein and mRNA levels, compared with normal thyroid tissue." (PMID 22682408, 2012). "Downregulation of ANXA3 was also reported in papillary thyroid cancer (PTC), and PTC patients with decreased ANXA3 expression exhibited substantially elevated lymph node metastasis scores and tumor growth." (PMID 34355022, 2021). "Whole genome sequencing was also applied in another research on 3 Brazilian families with hereditary papillary thyroid cancer (PTC), which found point mutation p.D283N on the ANXA3 gene (MIM No.106490)." (PMID 34355022, 2021).
periodontal disease (2 papers, 2023 to 2025). "Among the 92 inflammation-related genes evaluated using the TaqManTM Array Plate Human Inflammation Kit (Thermo Fisher Scientific, Waltham, MA, USA), four genes (TNFSF13B, ITGB2, ANXA5, and ANXA3) showed significant differential expression in patients with active periodontal disease." (PMID 40004451, 2025).
psoriasis (2 papers, 2010 to 2020). An autoimmune condition characterized by red, well-delineated plaques with silvery scales that are usually on the extensor surfaces and scalp. "In psoriasis, CCL4, GZMK and KLRF1 show significantly higher, while ADM, ANXA3, IL4, MMP9 and OLR1 show significantly lower expression levels in patients with arthritis negative psoriasis compared to patients with symptoms of arthritis." (PMID 20444268, 2010).
type II diabetes (2 papers, 2023 to 2025). "In a small study (of six non-union and six union cases), where half the patients had type II diabetes, it was found that Annexin A3 (ANXA3) levels were elevated in patients with delayed healing compared to uneventful healing." (PMID 40136615, 2025).
upper tract urothelial carcinoma (2 papers, 2014 to 2023). "For example, the high expression of ANXA3 has been closely associated with upper tract urothelial carcinoma, and patients with higher ANXA3 have been found to have a higher rate of postoperative recurrence." (PMID 36936694, 2023).
acute pancreatitis (1 paper, 2020). An acute inflammatory process that leads to necrosis of the pancreatic parenchyma. "miR-339-3p was reported to inactivate the Akt/mammalian target of rapamycin (mTOR) signaling pathway and to alleviate inflammation and edema caused by severe acute pancreatitis with acute lung injury in a mouse model by targeting annexin A3 (ANXA3)." (PMID 32264968, 2020).
adenoma (1 paper, 2016). A neoplasm arising from the epithelium. "Our results suggested that ANXA3 abundance increased stepwise in normal colorectal mucosa, adenoma and CRC tissues, indicating it being a candidate biomarker of colorectal carcinogenesis." (PMID 27661117, 2016). "Moreover, we observed that expression level of ANXA3 escalated in normal colorectal mucosa, adenoma and CRC tissues." (PMID 27661117, 2016). "Besides, western blot showed a stepwise increase of annexin A3 abundance in normal colorectal mucosa, adenoma and CRC tissues." (PMID 27661117, 2016). "Besides, using western blotting, we observed that expression level of ANXA3 increased stepwise in normal colorectal mucosa, adenoma and CRC tissues." (PMID 27661117, 2016). "Further validation was performed by western blot analysis of 3 representative proteins (i.e. ACO2, CES2 and ANXA3), using paired CRC, adenoma and normal fresh-frozen tissues of 3 patients." (PMID 27661117, 2016).
ankylosing spondylitis (1 paper, 2022). An autoimmune chronic inflammatory disorder characterized by inflammation in the vertebral joints of the spine and sacroiliac joints. "Upregulated of ANXA3, SORL1, and neutrophils can be key factors in the progression of Ankylosing Spondylitis." (PMID 35464477, 2022). "Upregulated of ANXA3, SORL1, and neutrophils may be a key factor in the progression of Ankylosing spondylitis." (PMID 35464477, 2022).
aortic regurgitation (1 paper, 2023). "In patients with aortic regurgitation (10 TAV and 11 BAV patients), the markers Annexin A3, tumour necrosis factor receptor superfamily member 11B, and Vigilin reached the significance, while the others demonstrated similar trends of enrichment." (PMID 37632572, 2023).
aortic valve disease (1 paper, 2023). "Immunostaining of the frozen valve tissues with anti-ANXA3 antibodies was positive for AVD patients and negative for healthy controls (healthy aortic valves collected post-mortem from two people without aortic valve disease)." (PMID 37632572, 2023).
Arterial thrombosis (1 paper, 2023). The formation of a blood clot inside an artery. "ANXA3 has also been associated with the occurrence of arterial thrombosis and multiple thrombotic events." (PMID 37035297, 2023). "Furthermore, increased ANXA3 mRNA expression is more pronounced in patients with arterial thrombosis or multiple thromboses, suggesting that ANXA3 is not only associated with thrombosis in PAPS but also with the severity of the thrombotic event." (PMID 37035297, 2023). "ANXA3 upregulation was more evident in cases of arterial thrombosis and multiple thrombotic events." (PMID 37035297, 2023).
asthma (1 paper, 2020). "In addition, other identified genes were LRRC48 and CETN2 in asthma-COPD, COL15A1, GIMAP6, and JAM2 in asthma-IPF, along with LMO7, TSPAN13, LAMA3, and ANXA3 in COPD-IPF." (PMID 31952466, 2020). "These genes included RBM42, STX5, and TRIM41 in asthma, CYP27A1, GM2A, LGALS9, SPI1, and NLRC4 in COPD, ATF3, PPP1R15A, ZFP36, SOCS3, NAMPT, and GADD45B in IPF, LRRC48 and CETN2 in asthma-COPD, COL15A1, GIMAP6, and JAM2 in asthma-IPF and LMO7, TSPAN13, LAMA3, and ANXA3 in COPD-IPF." (PMID 31952466, 2020).
atherosclerosis (1 paper, 2023). A disease characterized by the build-up of fatty material and calcium deposition in the arterial wall resulting in partial or complete occlusion of the arterial lumen. "Other Annexins, but not Annexin A3, have been shown to be involved in the development of atherosclerosis." (PMID 37632572, 2023).
benign prostatic hypertrophy (1 paper, 2011). "Finally, it was demonstrated that ANXA3 protein expression decreases from benign prostatic hypertrophy to localised pre-neoplastic lesions." (PMID 21266046, 2011).
bladder tumors (1 paper, 2021). "ANXA2, ANXA3, ANXA4, ANXA8, and ANXA9 were significantly increased in bladder tumor tissues, while ANXA6, ANXA7, and ANXA11 were significantly decreased." (PMID 34484309, 2021).
bone cancer (1 paper, 2021). A primary or metastatic malignant neoplasm affecting the bone or articular cartilage. "Similar findings were also presented by a research on bone-cancer induced pain (BCP), showing that downregulation of ANXA3 using shRNA substantially inhibited the expression of HIF1α and VEGF in the ipsilateral spinal cord and microglial cells of mice undertaken 21 days of bone cancer induction." (PMID 34355022, 2021).
brain injuries (1 paper, 2020). "A significant increase in ANXA3 levels was also found in brain injuries." (PMID 32455839, 2020).
clear renal cell carcinoma (1 paper, 2022). "We found that the expression level of ANXA1/2/4/5/6/7/8/13 in clear renal cell carcinoma tissue was higher than that in the kidney tissue, while the expression level of ANXA3/9/11 in the former was lower than that in the latter." (PMID 39290334, 2022).
COVID-19 (1 paper, 2020). A disease caused by infection with severe acute respiratory syndrome coronavirus 2. "ECM-associated proteins include several anticoagulant proteins (e.g. the annexin family members ANXA3, ANXA4, ANXA5, and ANXA8L1) of ECM-affiliated proteins were markedly diminished, which is consistent with the results indicating coagulation dysfunction in the COVID-19 patients." (PMID 33060566, 2020).
cyst (1 paper, 2015). A sac-like closed membranous structure that may be empty or contain fluid or amorphous material. "Western blot analyses showed expression of expected protein products for CK-19, ANXA3, CMBL and S100A13 in cyst fluids." (PMID 25978681, 2015). "ANXA3 and CMBL were both expressed in the cyst fluids of cPTCs and benign samples without obvious differences between the two groups." (PMID 25978681, 2015).
endometrial cancer (1 paper, 2017). Primary or metastatic malignant neoplasm involving the endometrium (mucous membrane that lines the endometrial cavity). "Western blotting verification data demonstrated that costars family protein ABRACL, phosphoglycerate mutase 2 were present only in endometrial cancer uterine aspirate while fibrinogen beta chain, annexin A3 were also present in healthy aspirates." (PMID 29312627, 2017). "From the discovery phase, four proteins (costars family protein ABRACL, phosphoglycerate mutase 2, fibrinogen beta chain, annexin A3) were found to be present in the uterine aspirate of endometrial cancers and not in healthy aspirates." (PMID 29312627, 2017). "In this study, western blot (WB) analysis from ten endometrial cancer vs six normal endometrium was used to validate the abundance of the four proteins which discriminate unambiguously between cases and controls (ABRACL, PGAM2, FGB, ANXA3)." (PMID 29312627, 2017).
glioblastoma (1 paper, 2023). The most malignant astrocytic tumor (WHO grade IV). "Interestingly, expressions of MMP2, chloride voltage-gated channel 3 (CLCN3), and annexin A3 (ANXA3) seem to be indispensable for the binding of CLTX to glioblastoma cells." (PMID 36721153, 2023).
Granuloma (1 paper, 2024). A compact, organized collection of mature mononuclear phagocytes, which may be but is not necessarily accompanied by accessory features such as necrosis. "Similar to TYMP and LAP3, the upregulated expression of ANXA3 in the blood samples may be closely related to angiogenesis in the granulomas of patients with PTB." (PMID 39023413, 2024).